CCL22 (C-C motif chemokine ligand 22)
Diseases named in the same sentence as CCL22 in open-access papers (continued):
Sharing a sentence is not in itself a finding about the gene and the disease.
tumor (continued). "CCL22 and TRPM5 were not available on the website, so we compared the other four genes’ IHC in normal tissue and tumor tissue." (PMID 33401247, 2020). "In our samples, the mRNAs of CCL22 and CCL28, two chemokines to which Tregs can respond, did not increase and CCL28 even decreased in tumor." (PMID 28290464, 2017). "Further, regression analysis only found weak correlation of Th17 cells with CCL22 (R = 0.385, P < 0.05), but not with CCL17 (P > 0.05), in the same tumor microenvironment." (PMID 25768730, 2015). "Ligands for CCR4 (e.g., CCL17 and/or CCL22) were in contrast to IL-6 and TGF-β not highly expressed in the tumor tissue, altogether indicating a conversion from CD8+ Tconvs rather than a tumor directed migration as the cause for the observed infiltration." (PMID 24212779, 2011). "However, the expression of several anti-inflammatory cytokines, such as CCL17, CCL22, IL-10, and TGF-β, and the M2 marker ARG1, was not significantly changed; these results were consistent with the transcriptome data in H22 tumor-bearing mouse liver tissue." (PMID 33710817, 2021). "The quantitative PCR results were consistent with the transcriptome results, showing that the expression of CCL2, CCL3, CCL5, and CXCL9, but not CCL17 or CCL22, was markedly higher in 1.5 mg/kg AAGL-treated tumor-bearing mouse livers than in those of control mice." (PMID 33710817, 2021). "Finally, CCL22 is also produced by primary cancer cells in breast, ovarian and HNSCC tumors but not cancer cell lines, suggesting a major role of tumor environmental factors." (PMID 33924428, 2021).
cancer (135 papers, 2013 to 2026). A tumor composed of atypical neoplastic, often pleomorphic cells that invade other tissues. "The chemokine CCL22 contributes to the recruitment of Treg and is therefore associated with poor prognosis in several types of cancer." (PMID 39232378, 2024). "CCL22 is elevated in many types of human cancers and elevated CCL22 is associated with poor prognosis in patients." (PMID 37207205, 2023). "CCL22 was found in several cancer types, often associated with high infiltration of Treg and low survival." (PMID 30572845, 2018). "Furthermore, cytokines Ccl2, Ccl4, Ccl7, Ccl22, and Il21r, which associated with an M2-like, pro-cancer macrophage phenotype, were found to be consistently downregulated at both days 5 and 10 post-challenge." (PMID 37066426, 2024). "In addition, IL-1β produced by cancer-associated fibroblasts (CAF) has also been described to favor the production of CCL22 by cancer cells in HNSCC." (PMID 33924428, 2021). "Disagreement between different studies regarding CCL22 genetic association with cancer might arises from mismatch in sample size and minor allele frequencies (MAFs) of the genetically different populations." (PMID 25031489, 2014). "Elevated CCL22 levels have been observed in melanoma and other cancers, promoting the accumulation of Foxp3+ Tregs, often in collaboration with CCL17." (PMID 40361472, 2025). "CCL22 can be secreted by dendritic cells and macrophages, and there are also studies indicating that CCL22 can be expressed by cancer cells." (PMID 40859900, 2025). "Though many studies have revealed the role of CCL22 in Treg accumulation and its impact on OS in cancer, the cellular source of CCL22 and its distribution in cancer tissue is still widely discussed and remains incompletely understood." (PMID 39232378, 2024). "The neutralization of CCL22 using a specific antibody has been shown to reverse these pro-tumorigenic effects, suggesting a therapeutic approach to mitigating cancer progression by targeting CCL22." (PMID 39286635, 2024). "Subsequent multivariate analysis was performed: CCL22 in cancer cells is an independent prognostic factor for a prolonged OS (Supplement 4), but not for PFS." (PMID 39232378, 2024). "Survival analysis revealed a significantly better OS for patients with high CCL22-expression in cancer cells (IRS>5)." (PMID 39232378, 2024). "CCL22, the second most highly regulated gene, has been reported to play significant roles in various cancer progressions." (PMID 39124881, 2024). "CCL22 promotes stemness of cancer cells with CCR4 expression, causing cancer cells migration and EMT, as shown on many types of cancers." (PMID 39513112, 2024). "CCL22 can be induced by cancer cell-derived IL-1α and the downstream recruitment of Tregs leads to a downregulation of the cell-surface antigen CTLA-4." (PMID 38928238, 2024). "M2 macrophages secrete anti-inflammatory cytokines such as IL-10, CCL18, and CCL22, which are beneficial to cancer cell growth." (PMID 37758759, 2023). "CCL22 has been reported to be crucial for migration of Tregs in several murine as well as human cancers." (PMID 37122749, 2023). "In this study, other cytokines of importance to cancer that were upregulated upon the use of cannabigerol included IL-28A, CCL22, FGF-21, and IL-33." (PMID 36923728, 2022). "The sensitivity of cancer patients to 5-FU therapy was regulated by the TAMs due to secretion of CCL22 and decreased apoptosis induced by 5-FU." (PMID 35742825, 2022). "Functionally, CCL22-stimulated hyperactivation of FAK was correlated with increased malignant progression of cancer cells." (PMID 35962191, 2022). "By suppressing the NF-κB/CCL22 axis in M2 macrophages, the fucoidan limits cancer cell mobility and reduces intratumoral CD4(+) regulatory T cells (Tregs) to enhance cancer therapeutics." (PMID 36109724, 2022). "Immunohistochemistry was used to detect the protein expression of CCL22 in cancer and adjacent normal tissues." (PMID 35176085, 2022).
cancer (continued). "Nevertheless, more recent data have provided evidence that in many types of cancers, immune cells are the exclusive producers of CCL22." (PMID 35805111, 2022). "The number of migrating and invading cancer cells of the ASO-HOTAIR+si-CCL22 group increased significantly than that of the ASO-HOTAIR+si-NC group (P<0.05)." (PMID 35176085, 2022). "It is also elaborated that M2 macrophages are associated with the dismal prognostic outcome of HCC, which enhances cancer invasion via the C-C motif chemokine 22 (CCL22)-induced epithelial–mesenchymal transition (EMT)." (PMID 36267406, 2022). "Among them, the CCL22 chemokine has been related to the immunosuppressive action exerted by TAMs in the TME of different types of cancer." (PMID 35887248, 2022). "Meanwhile, M2 macrophages can produce various matrix metalloproteinases (MMPs) and chemokines, such as MMP-2, MMP-7, MMP-9, CCL18, and CCL22, which promote the metastasis of cancer cells." (PMID 36685978, 2022). "Majority of TAMs are associated with Th2 response, secreting IL-10, CCL17, CCL2, CCL22, and TGF-β that favor cancer cell survival, and CCL22 that suppresses antitumor immunity by Treg action." (PMID 33522932, 2021). "We contribute to highlight the cooperation between TAM and NK cells through the secretion of IL-1β, TNF-α and IFN-γ, leading to the production of CCL22 by cancer cells." (PMID 33924428, 2021). "Seven upregulated genes (≥2.0-fold), Ccl24 (4.8-fold), Ccl17 (3.9-fold), S100a8 (2.9-fold), Tarm1 (2.7-fold), Anxa10 (2.4-fold), Ptgs2 (2.0-fold), and Ccl22 (2.0-fold) were detected as inflammatory and cancer-promoting genes." (PMID 34948416, 2021). "Referring to our analyzed cancer specimens, we showed that CCL22 expression was significantly decreased after coincubation of PIC with curcumin." (PMID 33809574, 2021). "CCL22 and CCL24 have been associated with M2-like polarization and worse prognosis in cancers and were also found to increase upon monocyte encapsulation in NSCLC spheroids." (PMID 34451433, 2021). "CCL17 and CCL22 promote stemness of cancer cells with CCR4 expression, drug resistance, stimulate the proliferation of cancer cells, and cause cancer cell migration and EMT, as shown on many types of cancers." (PMID 33182504, 2020). "Interestingly, lamin-deficient cancer cells were found to present higher expression levels of many inflammatory chemokines such as CCL2, CCL9, CCL22, CXCL9, and CXCL10." (PMID 40708945, 2025). "In addition to CCL2, CCL22, and IL-10, TAM-associated markers CCL5 and SPP1 (secreted phosphosprotein 1, also known as osteopontin, OPN) are promising targets for novel cancer immunotherapy." (PMID 40806751, 2025). "A higher expression of CCL22 has been described to be associated with a negative prognostic outcome in several cancers." (PMID 39232378, 2024). "CCR4 and its ligands CCL17 and CCL22 are also involved in cancer cell migration." (PMID 39114657, 2024). "CCL22-expression in cancer cells was significantly higher than in S/M." (PMID 39232378, 2024). "For example, CCL22 and TGF- β produced by the cancer cells and cancer-associated fibroblasts could recruit Tregs which in turn produce TGF-β and induce the conversion of naïve CD4+ T cells into Tregs." (PMID 38264664, 2023). "The chemokine CCL22, produced by macrophages, also plays a critical role in immune and inflammatory responses in the biology of cancer cells, and contributes to the development and progression of a number of human cancers." (PMID 36334221, 2023). "On the other hand, the changes between M0 and S + M0 were detected for chemokines CXCL12 (from 0.09 to 0.06 ng/mL, p = 0.0102), CXCL16 (from 0.58 to 0.45 ng/mL, p = 0.0012), and CCL22 (from 0.37 to 0.11 ng/mL, p = 0.0037), demonstrating the inhibitory effect of the cancer cell spheroids." (PMID 37445941, 2023). "CCL22 thus suppresses anti-cancer immune responses in cancer of different origins." (PMID 36175673, 2023).
cancer (continued). "Additionally, the mRNA levels of Treg chemokine receptors Ccr4, Ccr8, and Ccr10 as well as their ligands, Ccl1, Ccl17, and Ccl22 are significantly upregulated in the v-rasHa/ΔNp63α carcinomas compared to v-rasHa/Stuffer tumors or normal skin." (PMID 37638000, 2023). "CCL22 is found in a broad range of human cancers with potent pro-tumoral functions, while S100A8 and S100A9 are expressed by MDSCs in human CRC patients, are associated with the recruitment and immunosuppressive functions of MDSCs, and correlate with advanced CRC." (PMID 35658010, 2022). "CCL22 is expressed in alternative (M2) macrophage and in many types of cancer." (PMID 35960749, 2022). "However, immunosuppressive chemokines such as CXCL8, CXCL5, CXCL12, CCL2, and CCL22 were generally upregulated across the 13 cancer types." (PMID 34841742, 2022). "However, in other diseases, such as carcinoma, auto immune diseases, infections, or implantation, CCL22, the macrophage derived chemokine, and its receptor, CCR4, are well known for their role in the migration of Tregs." (PMID 35163802, 2022). "In cancers, CCL22 is unregulated by the suppression of miR-34a mediated by TGF-β." (PMID 34177907, 2021). "Previous research has reported that CCL22 is a prognostic predictor of various cancers." (PMID 31842422, 2019). "Tumors/cancer cells can secrete chemokines like CCL22 that recruit Tregs to the oncogenic site and help suppress effector functions of other T cells that may be necessary to eradicate cancer cells." (PMID 28116316, 2016). "Notably, CCL22 production in cancer cells is regulated by miR-34a, which suppresses the expression of this chemokine." (PMID 25743773, 2015). "Consequently, the observed reduction in CXCL12 and CCL22 levels in the presence of cancer cell spheroids may be partially due to the binding of these chemokines to their corresponding receptors." (PMID 40547518, 2025). "CCL22 might serve as a promising biomarker of poor prognosis in cancer." (PMID 38928238, 2024). "Thus, the reduction in CXCL12 and CCL22 in the presence of cancer cell spheroids may be partially explained by the binding of these chemokines to their receptors." (PMID 37445941, 2023). "We evaluated whether neutralization of CCL22 function contributes to the inhibition of TAM-mediated cancer cell invasion and found that treatment with a CCL22 neutralizing antibody (Ab) markedly decreased the number of invaded ESCC cells in cocultures with pol-TAMs or pri-TAMs." (PMID 35962191, 2022). "Moreover, it has been noted that two CCR4 ligands -CCL17 and CCL22-, are overexpressed in lymphoid malignancies such as Hodgkin’s lymphoma (HL), and in many other types of human cancers including ovarian, breast, esophageal and gastric cancers." (PMID 35211124, 2022). "Moreover, the microbiota has been suggested to favor CCL22 secretion by cancer cells in CRC." (PMID 33924428, 2021). "Macrophages are known to recruit T cells via chemokines such as CCL5 and CCL22, and their spatial coupling with lymphocytes in OCRC aligns with studies describing macrophage-driven T-cell chemotaxis in other cancer types." (PMID 41301691, 2025). "In malignant tumors, the polarized M2 macrophages produce and secrete cytokines such as CCL18, CCL20, CCL22, IL10, TGFB1, and GDF15." (PMID 39272860, 2024). "In this study, the expression of CCL22 and LncRNA HOTAIR mRNA in cancer tissues and adjacent normal tissues of NSCLC patients showed significant differences." (PMID 35176085, 2022). "Many macrophages-derived cytokines present in the TME have already been verified to affect the response of cancer cells to chemotherapy like CCL2, CCL22, IL-6 and CCL18." (PMID 36151545, 2022). "Among the proteins differentially present in cancer vs. control were six common to both local and metastatic PDAC: Up—GDF15, TIMP1, and IL1RL1; Down—CCL22, APP, and CLEC1B." (PMID 33334063, 2020).
cancer (continued). "The main factors affecting the biological activity of cancer cells are IL-10, IL-6, TGF-β, VEGF, CCL18, CCL22, and microRNA." (PMID 32456078, 2020). "CXCL12, CCL22 and CCL17 have been described as critical factors for T-reg attraction in different cancer types." (PMID 28987144, 2017). "CCL22 and CCR4 also play an important role in cancer growth and metastasis, thus many CCR4 receptor antagonists as well as an anti-CCR4 antibody are being developed in the pharmaceutical industry." (PMID 25245466, 2014). "Our findings have translational relevance by suggesting future clinical investigation of the TRAIL innate immune pathway, CCL22, and TLR7 in toxicity of radiation or other cancer therapeutics and in other inflammatory lung or skin conditions, and have implications for radiation countermeasures." (PMID 39808500, 2025). "However, despite its importance in cancer biology, the precise function of MDC/CCL22 in the immune system remains poorly understood." (PMID 37685890, 2023). "Our experiment also verified that CCL22 was elevated in the HNSCC cell line CNE2, indicating that the CCL22/CCR4 axis might contribute to cancer progression in HNSCC." (PMID 36834729, 2023). "For this, it may be helpful to examine the chemokines CCL22 and CCL1 in the TME of EC, as has been reported for other cancer entities." (PMID 36098901, 2022). "CCR4 is bound by CCL22, which is positively coexpressed with OLFML2B in 22 cancers." (PMID 35873458, 2022). "CCL5, XCL1, XCL2, CCL17, CCL22, and CCL19 showed a positive correlation with DEF6 in most cancers, and DEF6 may function in regulating these chemokines in cancer." (PMID 36686789, 2022). "We collected 30 clinical samples of cancer and adjacent normal tissues from the patients with NSCLC, using real-time quantitative polymerase chain reaction (RT-qPCR) to detect the LncRNA HOTAIR and CCL22 mRNA expression in tissues." (PMID 35176085, 2022). "Finally, we carried out qRT-PCR analysis and concluded that mRNA expression levels of CCL22 and IL10 were higher in HNSCC cancer tissues than in normal tissues." (PMID 35480305, 2022). "TLS in other cancers have been identified and defined by expression of a number of chemokines that are involved in TLS neogenesis: CCL19, CCL21, CXCL12, CXCL13, CCL17, and CCL22." (PMID 34943886, 2021). "The efficient uptake of MP by M2 macrophages accompanied by increase production of CCL22 and CD209, which recruit regulatory T cells and dendritic cells into cancer tissue, enhanced the M2 immune activity and can be used to target macrophages involved in cancer progression." (PMID 33790914, 2021). "In addition, the four overlapping target genes of miR-7977 (CCL22, STK4, HSPA1B, and ACTR2) in all three databases were reported to have a key role in cancer formation and metastasis." (PMID 32328453, 2020). "Chronic hypoxia also enhances the effect of the described chemokines on cervical and ovarian cancer cells by increasing the expression of the CCR4, CCL17/TARC, and CCL22/MDC receptor, the latter of which are responsible for an increase in the proliferation of cancer cells." (PMID 32781743, 2020). "CCL22 and CCL17 are produced by cancer cells and are known to induce immune evasion in cancer." (PMID 33163184, 2020). "Six were common for cancer stage (Up: GDF15, TIMP1, IL1RL1; Down: CCL22, APP, CLEC1B)." (PMID 33334063, 2020). "In the same study, the authors also showed that as a result of silencing IL-1A in pancreatic tumour cells (PaTu), CCL22 production was inhibited in PBMC, whereas inhibition of IL-1A or IL-1B in mammary 4T1 cancer cell line resulted in impaired CCL22 production in splenocytes." (PMID 29760166, 2018). "Both cancer cell lines and live mf significantly (p = 0.001) upregulated the production of IP-10 and CCL22, while IL-6 production was significantly upregulated only by cancer cell lines and not by mf." (PMID 29668679, 2018).